BNIP3 (BCL2 interacting protein 3)
Diseases named in the same sentence as BNIP3 in open-access papers (continued):
Sharing a sentence is not in itself a finding about the gene and the disease.
pancreatic cancer (continued). "Conversely, the behaviour of BNIP3 is characterized by a negative correlation between its expression and pancreatic cancer." (PMID 22291707, 2012). "The activation of BNIP3 that initiates opening of the mitochondrial permeability transition pore and cell death in the absence of caspase activation has been previously reported in neonatal cardiac myocytes but not in pancreatic cancer cells." (PMID 28968982, 2017). "However, to the best of our knowledge, the mechanism of HIF-1α-mediated BNIP3 induction in pancreatic cancer cells has not yet been fully elucidated." (PMID 28968982, 2017). "In addition, the restoration of BNIP3 expression in the pancreatic cancer BNIP3-negative cell line Capan-1 was examined with regard to the induction of the mitochondrial pathway of apoptosis." (PMID 28968982, 2017). "The expression of the protein was absent in several pancreatic cancer cell lines and it was downregulated in 9 samples of pancreatic adenocarcinoma compared with 8 samples of normal pancreas, due to increased methylation of the BNIP3 promoter." (PMID 28968982, 2017). "First, neither CSPG4low HPDE cells nor pancreatic cancer cell lines showed significant elevation of CSPG4 expression, although hypoxia greatly increased expression of other hypoxic markers, such as BNIP3, EPO (data not shown), and NIX." (PMID 24932730, 2014).
glioma (40 papers, 2013 to 2025). A benign or malignant brain and spinal cord tumor that arises from glial cells (astrocytes, oligodendrocytes, ependymal cells). "Collectively, autophagy contributed to silibinin-induced glioma cell death via causing BNIP3-mediated mitochondria damage and nuclear translocation of AIF." (PMID 32801360, 2020). "Furthermore, amplification peaks of oncogenes (PIK3C2B, PDGFRA, EGFR, CDK4), and deletion peaks of tumor suppressor genes (TUSC1, CDKN2A, CDKN2B, PTEN, FAS, BNIP3) were detected in the gliomas with a high risk score." (PMID 32023222, 2020). "Thus, these indicated that BNIP3 contributed to silibinin-induced glioma cell death via causing mitochondrial damage and nuclear translocation of AIF." (PMID 32801360, 2020). "Thus, BNIP3 contributed to silibinin-induced glioma cell death via causing mitochondrial damage." (PMID 32801360, 2020). "This study explored whether EMAP-II can enhance the cytotoxic effects of TMZ on glioma stem cells (GSCs) and the possible mechanisms associated with Bcl-2/adenovirus E1B 19 kDa protein-interacting protein 3 (BNIP3)-mediated mitophagy facilitated by miR-24-3p regulation." (PMID 29632473, 2018). "This enhances the YTHDF2-BNIP3 interaction and modulates BNIP3-dependent, mitophagy-mediated metabolic reprogramming, consequently impacting glioma stemness and invasion." (PMID 41463052, 2025). "Meanwhile, BNIP3, activated by Cer, can induce mitophagy and lead to the death of malignant glioma cells." (PMID 37807060, 2023). "Out of these NRGs, 19 NRGs (EGLN3, HILPDA, HMBS, HYOU1, BNIP3, etc.)were found to be enriched in glioma tissues while 13 genes (SLC4A1, IL6, EPAS1, ACE, HMOX1, etc.)were decreased compared to normal tissues." (PMID 37934582, 2023). "Autophagy activated by silibinin contributes to glioma cell death via induction of oxidative stress‐mediated BNIP3‐dependent nuclear translocation of AIF." (PMID 35212145, 2022). "In glioma cell lines U87 and U251, silibinin promoted the up-regulated expression of BNIP3, as well as translocation of the protein into the mitochondria by activating autophagy." (PMID 35401195, 2022). "In conclusion, we demonstrate in this study that FOXO3a protects glioma cells against TMZ treatment by activating BNIP3-mediated mitophagy, which inhibits the nuclear translocation of AIF and DNA DSBs via inhibition of oxidative stress." (PMID 33879840, 2021). "Knockdown of FOXO3a with siRNA markedly prevented TMZ-induced BNIP3 upregulation and autophagy activation and exacerbated glioma cell death." (PMID 33879840, 2021). "To elucidate the role of BNIP3 in silibinin-produced toxicity in glioma cells, we used SiRNA to knock down BNIP3 and examined its effect on glioma cell death and mitochondrial damage." (PMID 32801360, 2020). "Induction of HIF-1α and its target BNIP3 was also detectable in LNT-229 glioma cells as well as in LIM1215 and SW948 cells in the presence of cetuximab and bevacizumab in hypoxia." (PMID 33092032, 2020). "It was reported that overexpressed BNIP3 contributed to baicalein-induced apoptosis in osteosarcoma cells, hydrogen peroxide-induced autophagic death in glioma cells, and doxorubicin-induced necrosis in cardiac myocytes." (PMID 32801360, 2020). "These indicated that silibinin promoted BNIP3 accumulation on mitochondria, as well as upregulated its expression in glioma cells." (PMID 32801360, 2020). "Collectively, autophagy contributes to silibinin-induced glioma cell death via promotion of oxidative stress-mediated BNIP3-dependent nuclear translocation of AIF." (PMID 32801360, 2020). "In contrast, nuclear localization of BNIP3 contributes to blockage of apoptosis in glioma cells through repression of pro-apoptotic genes." (PMID 30307949, 2018). "To evaluate the protein levels of BNIP3, we analyzed the rat glioma tissues (n=6) by immunohistochemistry (IHC)." (PMID 28977881, 2017).
glioma (continued). "To define the role of BNIP3 in gliomas, we measured BNIP3 mRNA expression in glioma human samples, rat tissues, and glioma cell lines by quantitative real-time PCR." (PMID 28977881, 2017). "BNIP3 is localized in the nucleus in glioma cells, and miR-145 inhibits BNIP3 expression by binding to the 3’ untranslated region of its mRNA." (PMID 28977881, 2017). "Co-transfection of luciferase reporter with the miR-145 mimics into U87 and U251 cells decreased expression of BNIP3, indicating that BNIP3 is a direct target of miR-145 in glioma cells." (PMID 28977881, 2017). "Compared to control brain tissues, the expression of BNIP3 in rat glioma tissues was increased (magnification: 100, 200, 400)." (PMID 28977881, 2017). "MiR-145 promotes apoptosis of glioma cells by inhibiting BNIP3, resulting in the inhibition of Notch signaling." (PMID 28977881, 2017). "Western analysis demonstrated that BNIP3 expression was higher in human glioma samples compared with normal samples, and in rat glioma tissues and glioma cell lines compared with rat normal brain tissues." (PMID 28977881, 2017). "Here we show that miR-145 expression is decreased in human glioma samples, rat glioma tissues, and glioma cell lines, while expression of BNIP3 is increased." (PMID 28977881, 2017). "Our results demonstrate that BNIP3 is localized in the nucleus of glioma cells, and serves as a target of miR-145." (PMID 28977881, 2017). "A recent study has indicated that the nuclear BNIP3 forms a complex with histone deacetylase 1 (HDAC1) and PTB-associating splicing factor (PSF) to down-regulate AIF expression in glioma cells, leading to their resistance to temozolomide-induced cell death." (PMID 28977881, 2017). "First, up-regulation of miR-145 and knockdown of BNIP3 decreased the protein expression of Notch1, Hes1, and p21 in glioma cells." (PMID 28977881, 2017). "Second, down-regulation of miR-145 and up-regulation of BNIP3 increased the protein expression of Notch1, Hes1, and p21 in glioma cells." (PMID 28977881, 2017). "BNIP3-mediated reduction in AIF expression leads to decreased temozolomide-induced apoptosis in glioma cells and transcriptional repression function for BNIP3 causing reduced AIF expression and increased resistance to apoptosis." (PMID 27861627, 2016). "In glioma cells, ROS induce autophagy by inhibiting mTOR in a BNIP3-dependent manner (BNIP3: BCL2/adenovirus E1B 19 kDa protein-interacting protein 3)." (PMID 25803050, 2015). "Taken together, we have discovered a novel transcriptional repression function for BNIP3 conferring a TRAIL resistance in glioma cells." (PMID 23579274, 2013). "Herein, we have discovered when BNIP3 nuclear expression is knockdown in glioma cell lines and in normal mouse astrocytes, TRAIL and its death receptor, death receptor-5 (DR5) expression is increased." (PMID 23579274, 2013). "Overall, nuclear BNIP3 downregulates DR5 expression in glioma cells, leading to resistance to TRAIL-induced cell death." (PMID 23579274, 2013). "Furthermore, the absence of DR5 in GFAP positive astroglial cells is linked to the expression of BNIP3, a transcriptional inhibitor, which mitigates DR5 expression and confers resistance to TRAIL in gliomas." (PMID 38802941, 2024). "Endothelial monocyte-activating polypeptide-II was found to enhance TMZ toxicity in glioma stem cells by inducing BNIP3-mediated mitophagy, but it remains elusive whether TMZ alone could trigger mitophagy in glioma cells." (PMID 33879840, 2021). "Therefore, FOXO3a protects glioma cells against TMZ-induced DNA DSBs via promotion of BNIP3-mediated mitophagy." (PMID 33879840, 2021). "Furthermore, Nrf2 has also been proven to induce mitophagy by promoting NIX and BNIP3 expressions in glioma and myocardial ischemia, respectively." (PMID 33628368, 2021). "It was reported that BNIP3 contributed to ceramide-triggered lethal mitophagy in glioma cells." (PMID 33879840, 2021).
glioma (continued). "Therefore, in this study, we investigated the role of FOXO3a in TMZ-induced glioma cell death and its relationship with BNIP3-mediated mitophagy." (PMID 33879840, 2021). "Moreover, LDH release assay proved that knockdown of BNIP3 with SiRNA significantly prevented the glioma cell death induced by silibinin." (PMID 32801360, 2020). "Suppression of BNIP3 by upregulation of miR-145 was reported to induce apoptosis in glioma cells." (PMID 32801360, 2020). "This indicated that BNIP3 might play a role in regulation of silibinin-induced nuclear translocation of AIF in glioma cells in vivo." (PMID 32801360, 2020). "In astrocytes and glioma cells, BNIP3 is expressed in the nucleus." (PMID 30307949, 2018). "Arsenic trioxide and ceramide can upregulate BNIP3 expression to induce mitophagy in glioma." (PMID 29632473, 2018). "Compared with controls, BNIP3 mRNA levels in human glioma samples, rat glioma tissues, and glioma cell lines were increased, suggesting that there may be a negative correlation between miR-145 and BNIP3." (PMID 28977881, 2017). "Immunofluorescence revealed abundant BNIP3 staining in the nucleus of glioma tissues." (PMID 28977881, 2017). "In addition, our results indicate that BNIP3 inhibits apoptosis of glioma cells by regulating the Notch signaling pathway." (PMID 28977881, 2017). "BNIP3 fails to associate with mitochondria in gliomas and promote cell death, due to its nuclear localization." (PMID 28977881, 2017). "Collectively, these results indicate that BNIP3 inhibits apoptosis of glioma cells." (PMID 28977881, 2017). "Over-expression of miR-145 or suppression of BNIP3 induced glioma cell apoptosis." (PMID 28977881, 2017). "In order to examine whether BNIP3 regulates glioma cells apoptosis, cells were transfected with BNIP3 siRNA or BNIP3-pEX-2 expression vector." (PMID 28977881, 2017). "Together, our results indicate that miR-145 increases apoptosis of glioma cells by directly inhibiting BNIP3, resulting in the inhibition of Notch signaling, and suggest that miR-145 may serve as a novel therapeutic target in malignant gliomas." (PMID 28977881, 2017). "Our discovery that nuclear BNIP3 represses DR5 expression in both glioma cells and normal astrocytes, suggests that TRAIL treatment could be effective if nuclear BNIP3 transcriptional repression was inhibited." (PMID 23579274, 2013). "Interestingly, miR-145 and BNIP3 regulate glioma cell apoptosis by modulating Notch signaling." (PMID 28977881, 2017). "However, in glioma cells, BNIP3 is localized in the nucleus, and inhibits apoptosis." (PMID 28977881, 2017). "An EdU-DNA synthesis assay demonstrated that BNIP3 overexpression induced protective autophagy in glioma cells, whereas reducing CANX expression in BNIP3-overexpressing cells adversely affected their proliferative ability." (PMID 39990231, 2025). "In this study we investigated the role of FOXO3a in regulating the sensitivity of glioma cells to temozolomide (TMZ) and its relationship with BNIP3-mediated mitophagy." (PMID 33879840, 2021). "In summary, we found in this study that TMZ inhibited glioma cell growth and induced DNA DSBs and nuclear translocation of AIF in vitro and in vivo, which was accompanied by BNIP3-mediated mitophagy and FOXO3a upregulation." (PMID 33879840, 2021). "Correspondingly, TMZ-induced glioma cell death, nuclear translocation of AIF and upregulation of γ-H2AX were all enhanced when BNIP3 was knocked down." (PMID 33879840, 2021). "Here, we present a strong evidence that miR-145 inhibits the expression of BNIP3 by binding to its 3′-UTR in glioma cells, and we demonstrate an inverse correlation between miR-145 and BNIP3 expression in glioma tissues." (PMID 28977881, 2017).
glioma (continued). "Thus, we analyzed whether BNIP3 is localized in the nucleus in rat glioma tissues to form gliomas." (PMID 28977881, 2017). "BNIP3 is a direct transcriptional target of HIF-1α, which has been shown to regulate BNIP3 expression in response to hypoxia and in glioma cells treated with ceramide." (PMID 24824755, 2014). "We previously found that BNIP3 is localized to the nucleus in GBM tumors and suppresses cell death in glioma cells." (PMID 23579274, 2013). "Herein, we have discovered that BNIP3 localized to the nucleus represses DR5 expression and blocks TRAIL-induced apoptosis in glioma cells." (PMID 23579274, 2013). "However, BNIP3 upregulation appeared to be a better prognosis indicator in kidney renal clear cell carcinoma (KIRC) and low-grade glioma (LGG)." (PMID 35912211, 2022). "Moreover, high levels of the HIF1-α transcriptional target BCL2 Interacting Protein 3 (BNIP3) mRNA, another mitophagy receptor, are found in EV produced by hypoxic glioma cells." (PMID 33511121, 2020). "Knockdown of BNIP3 with SiRNA inhibits silibinin-induced mitochondrial depolarization, accumulation of mitochondrial superoxide, and AIF translocation from mitochondria to nuclei, as well as prevents glioma cell death." (PMID 32801360, 2020). "Knockdown of BNIP3 with SiRNA inhibited silibinin-induced mitochondrial depolarization, accumulation of mitochondrial superoxide, and AIF translocation from mitochondria to nuclei, as well as prevented glioma cell death." (PMID 32801360, 2020). "BNIP-3 has been shown to inhibit apoptosis in GB cells by acting as a transcriptional repressor of the death receptor-5 expression and therefore preventing TRAIL-induced cell death in gliomas." (PMID 32867190, 2020). "For instance, hypoxia induced by antiangiogenic therapy increases the levels of the autophagy-mediating BCL2-interacting protein 3 (BNIP3) protein, which induces the activation of autophagy in U87 and T98G glioma cell lines as a cytoprotective adaptive response, thereby promoting cell survival." (PMID 33123479, 2020). "In contrast, knockdown of BNIP3 with SiRNA obviously inhibited silibinin-induced mitochondrial depolarization, accumulation of mitochondrial superoxide and nuclear translocation of AIF, as well as rescued glioma cell death." (PMID 32801360, 2020). "Strikingly, a similar mechanism (BNIP3/BNIP3L-mediated autophagic cell death) has also been proposed for ATO in non-GSC glioma cells, indicating that Gos and ATO might target overlapping pathways to promote cell demise of GSCs." (PMID 30871073, 2019). "In fact, we could recently show that HMOX-1 is induced after Gos-mediated mitochondrial dysfunction in non-GSC glioma cells and that this is accompanied by induction of BNIP3 and Nix (BNIP3L), leading to an autophagic type of cell death." (PMID 30871073, 2019). "Moreover, BNIP3 knockdown reinforced TMZ-induced increases in mitochondrial superoxide levels and the nuclear translocation of AIF, as well as enhanced intracellular ROS levels and glioma cell death, all of which were consistent with the findings reported when autophagy was blocked." (PMID 33879840, 2021). "However, the Notch regulation by BNIP3 in glioma cells has not been investigated." (PMID 28977881, 2017).